TOP2A (DNA topoisomerase II alpha)
Diseases named in the same sentence as TOP2A in open-access papers (continued):
Sharing a sentence is not in itself a finding about the gene and the disease.
breast carcinoma (continued). "Such interaction between YAP1/TAZ/TEAD-bound enhancers with promoters via chromatin looping has been reported in the MYC and TOP2A genes in an epithelial human breast cancer cell line." (PMID 35619099, 2022). "Several retrospective analyses have suggested a correlation between TOP2A status and response to anthracyclines in breast cancer, both in neoadjuvant and adjuvant treatment." (PMID 35409939, 2022). "As one of the important factors of DNA unlinking, TOP2A has been involved in the occurrence and development of many different cancers, including bladder urothelial carcinoma, prostate cancer, breast cancer, colon cancer and liver cancer." (PMID 35778520, 2022). "Compared with normal tissues, TOP2A mRNA is significantly expressed in bladder cancer, head and central nervous system cancer, breast cancer, cervical cancer, colorectal cancer, and other cancers." (PMID 35033076, 2022). "Previous studies have reported that TOP2A constitutes a marker for predicting prognosis and response to various cancer therapies, for instance, breast cancer, soft tissue sarcomas, as well as clear cell renal cell carcinoma." (PMID 35884419, 2022). "High expression of TOP2A in many types of tumors, such as non-small cell lung cancer, hepatocellular carcinoma, and breast cancer, has been proven to be a dependable proliferation marker and is associated with disease progression and poor prognosis." (PMID 35912241, 2022). "Many studies have shown that TOP2A has the capacity to predict the sensitivity of breast cancer to anthracyclines." (PMID 35784467, 2022). "High expression of TOP2A occurs most often in breast cancer, where it is strongly correlated with the patients' disease-free survival and total survival, and thus it is regarded as a valuable prognostic biomarker for breast cancer." (PMID 36247089, 2022). "The expression of TOP2A in cancer tissues such as kidney cancer, liver cancer, and breast cancer were significantly higher than that in normal tissues, and TOP2A gene expression was highest in hepatocellular carcinoma stage III." (PMID 35033076, 2022). "Alteration of TOP2A was reported to be related with restricted responsiveness to anthracycline-based chemotherapy in breast cancer." (PMID 35444614, 2022). "Five hub genes, RRM2, TOP2A, PBK, MELK, and NUSAP1, which are associated with breast cancer pathogenesis, are gradually upregulated from NME to DCIS and then downregulated in IDC." (PMID 34094915, 2021). "TOP2A protein levels are used as a predictor of response to epirubicin as a neoadjuvant treatment for breast cancer." (PMID 34116668, 2021). "Several studies highlighted the importance of TOP2A, and elevated TOP2A expression can serve as a prognostic biomarker in multiple malignancies, including lung, colon, and breast cancer." (PMID 33807717, 2021). "These downstream effects of TOP2A expression, along with the enhanced expression of TOP2A observed in metastatic luminal breast cancer and prostate cancer, indicate a potential role in all five stages of the metastatic cascade." (PMID 34591244, 2021). "TOP2A amplification is a known predictive marker of anthracycline-based neoadjuvant chemotherapy efficacy in patients with breast cancer." (PMID 34771654, 2021). "HER2 and TOP2A, which are important biomarkers of breast cancer, were also detected in Saudi CRC patients but in lower amplifications compared to Saudi breast cancer patients." (PMID 33440689, 2021). "Alterations in TopoisomeraseII alpha (TOP2A), commonly amplifications, were seen in different breast cancer subtypes." (PMID 35053185, 2021). "In breast cancer, TOP2A amplification was correlated with sensitivity to anthracycline‐based neoadjuvant chemotherapy, and TOP2A was identified as a predictive marker." (PMID 33527765, 2021). "This study shows that hub genes associated with breast cancer pathogenesis, namely RRM2, TOP2A, PBK, MELK, and NUSAP1, are gradually upregulated from NME to DCIS and then downregulated in IDC." (PMID 34094915, 2021).
breast carcinoma (continued). "While there was no differential benefit from anthracycline-based therapy in patients with HER2+ vs HER2− breast cancer in this study, those with tumor TOP2A-amplification (N = 92) (ratio >2) had a significantly improved RFS and OS with CEF." (PMID 34625570, 2021). "Hub genes, namely TOP2A, MELK, PBK, NUSAP1, and RRM2, are closely associated with the occurrence and pathogenesis of breast cancer." (PMID 34094915, 2021). "TOP2A plays an important role in promoting tumorigenesis in breast cancer, ovarian cancer, prostate cancer, colon cancer, and acts as biomarker in renal clear cell cancer prognosis status." (PMID 33154194, 2020). "Numerous studies indicated that TOP2A is highly expressed in a variety of malignant tumors, such as colorectal cancer, meningioma, breast cancer, adrenocortical carcinoma, NSCLC and SCLC." (PMID 33186389, 2020). "Based on integrated bioinformatic analysis, the present study has identified 321 DEGs and six hub genes (CDK1, CCNA2, TOP2A, CCNB1, KIF11, and MELK) that are associated with breast cancer tumorigenesis and progression." (PMID 31428132, 2019). "The functional and clinical roles of TOP2A have been demonstrated in human cancers, including prostate cancer, breast cancer, and nasopharyngeal carcinoma." (PMID 31886163, 2019). "A most well known disease associated with TOP2A is female breast cancer, it is usually deleted or amplified simultaneously with ERBB2, thus the two genes are commonly co-tested in breast cancer patients for further proper use of anticancer agent herceptin." (PMID 31528121, 2019). "Previous researches have confirmed that upregulated TOP2A has unfavorable prognosis in breast cancer in both 5-year disease-free survival 20 and adjuvant treatment." (PMID 31777591, 2019). "In HBC, ERBB2 and TOP2α are frequently co-amplified and co-expressed in breast cancer patients and have also been proposed as prognostic biomarkers." (PMID 31301170, 2019). "Other works, however, suggested that TOP2α should be used as an independent breast cancer prognostic and predictive biomarker." (PMID 31301170, 2019). "The association between the oral contraception and the TOP2α RNA levels has not yet been reported, either in humans or in cats, but in the present study, the animals medicated with oral contraceptive showed mammary carcinomas with lower TOP2α RNA levels." (PMID 31301170, 2019). "TOP2α status has several important implications in breast cancer, however standard tools and cut-off values for estimating TOP2α status have not yet been established." (PMID 31301170, 2019). "The expressions of cyclin D1, TOP2A, and RacGAP1 were found to be slightly up-regulated in the primary breast cancer cell samples treated with E2." (PMID 31293425, 2019). "For instance, TOP2A (topoisomerase II alpha), a specific marker of cell proliferation, is the primary molecular target of anthracyclines used for treating breast cancer." (PMID 30886771, 2019). "In this work we evaluated the ERBB2 and TOP2α gene status and RNA levels in a collection of feline mammary tumors using the disease-free tissue sample collected from the same donor as reference and these data were associated with clinicopathological features." (PMID 31301170, 2019). "In modern tailored therapy, TOP2A overexpression can be a poor prognostic factor in luminal B breast cancer." (PMID 29928479, 2018). "Temozolomide alone decreases p-AURKB and p-TOP2A expression in breast cancer cells compared to controls." (PMID 30038716, 2018). "A continuous value of TOP2A expression was also shown to be the significant prognostic factor in luminal B breast cancer in Cox regression analysis (HR 1.07; 95% CI, 1.02–1.12, P = 0.005)." (PMID 29928479, 2018). "The current study demonstrated that TOP2A protein overexpression was associated with worse DFS, especially shorter DMFS in stage I-II luminal breast cancer." (PMID 29587760, 2018).
breast carcinoma (continued). "In conclusion, our study indicates that TOP2A overexpression is a marker for poor prognosis, especially in cases of luminal B breast cancer." (PMID 29928479, 2018). "In consistent with these three studies, the current study demonstrated that high TOP2A protein expression was a worse prognostic factor in early stage luminal breast cancer." (PMID 29587760, 2018). "Further large-scaled, prospective studies with standardized method of measuring TOP2A are required to overcome the limitations of current study and confirm the utility of TOP2A protein in luminal breast cancer." (PMID 29587760, 2018). "TOP2A amplification is frequent in breast cancer correlating with larger, higher grade tumors and positive lymph nodes." (PMID 30038716, 2018). "A meta-analysis of adjuvant randomized trials comparing anthracycline-based treatment with CMF suggested that TOP2A amplified predicted responsiveness to anthracycline-based chemotherapy in patients with early breast cancer." (PMID 29928479, 2018). "In HER2 positive breast cancer, TOP2A amplified (HR 0.30, 95% CI 0.085–1.07, p = 0.063) appeared to be a better prognostic factor." (PMID 29928479, 2018). "Cancers with Top2a gene amplifications (e.g. Her2-positive breast cancers) often exhibit enhanced sensitivity to various Top2 poisons." (PMID 30170832, 2018). "The current study enrolled a relatively large group of homogenously early luminal breast cancer patients (stage I-II), and try to confirm the prognostic value of TOP2A protein on this subtype of breast cancer classified by current IHC approach." (PMID 29587760, 2018). "The clinical significance and best assessment of TOP2A status need to be re-evaluated under modern tailored therapy based on breast cancer subtype." (PMID 29928479, 2018). "Cox regression analysis showed that TOP2A overexpression is a significant prognostic factor in luminal B breast cancer (hazard ratio (HR) 4.00, 95% confidence interval (CI) 1.65–9.54, p = 0.002)." (PMID 29928479, 2018). "Another most recent study evaluated an even larger database of TOP2A mRNA in 4142 breast cancer patients, and reported again that high TOP2A mRNA expression was only significantly associated with poor prognosis in luminal breast cancer." (PMID 29587760, 2018). "TOP2A, a latent biomarker for cancer therapy, has been detected in various types of cancer, including breast cancer, hepatocellular carcinoma and glioma." (PMID 30544723, 2018). "Considering the comprehensiveness and the reproducibility of the results of previous studies, 10% of TOP2A expression can be a reasonable cut-off value for predicting recurrence in luminal B breast cancer." (PMID 29928479, 2018). "Third, a small number of cases and events in HER2 positive breast cancer is underpowered to make conclusion about the predictive value of TOP2A amplified in anthracycline treatment." (PMID 29928479, 2018). "In an exploratory analysis, the ROC curve indicated an optimal TOP2A expression cutoff value of 11.5% for predicting 5-year RFS in luminal B breast cancer, which is approximate to 10% of TOP2A expression adopted in this study." (PMID 29928479, 2018). "Peter Fritz and his colleagues enrolled 225 un-subtyped operable breast cancer patients, and found TOP2A predicted prognosis only in hormone receptor positive disease." (PMID 29587760, 2018). "Another two studies consistently reported that TOP2A mRNA expression was highly prognostic only in luminal type breast cancer." (PMID 29587760, 2018). "Expression of TOP2A was higher in proliferative subtypes of breast cancers such as triple negative and HER2-enriched diseases than luminal type." (PMID 29587760, 2018). "Our findings supported a previous report of a pooled analysis of four independent gene expression data sets evaluating the prognostic value of TOP2A RNA expression in luminal breast cancer." (PMID 29928479, 2018).
breast carcinoma (continued). "TOP2A is highly expressed in some types of cancers, including breast cancer, hepatocellular carcinoma, and glioma, and serve as a biomarker for these cancers." (PMID 30544723, 2018). "Nine genes in this module – Akt1, Brca2, Ccnd1, Dnmt1, Mki67, Palb2, Rrm1, Timeless, and Top2a – are known human breast cancer genes according to the MalaCards database; four of them are hub genes." (PMID 28212608, 2017). "Changes in intracellular TOP-2a expression and activity form another important mechanism of breast cancer resistance to chemotherapy." (PMID 29290947, 2017). "As TOP2A has been associated with response to anthracycline-based chemotherapy and aromatase inhibitors are widely used for breast cancer treatment, we explored if the expression of these genes and the intrinsic subtype of breast cancer could be associated with the development of recurrences." (PMID 28832682, 2017). "Co-amplification of ERBB2 and TOP2A has been reported in breast cancer cases, which has been attributed to their proximity to chromosome 17 (17q12 and 17q21.3-22, respectively)." (PMID 28915696, 2017). "We chose TOP2A because it is used for breast cancer diagnostics and because, as a target for anthracyclines and topoisomerase II inhibitors, it also has a direct predictive therapeutic value in many cancers." (PMID 27259241, 2016). "This further supports the potential role of TOP2A in drug response to docetaxel in breast cancer cells." (PMID 26824188, 2016). "Based on our previously identified drug resistance related signature genes for breast cancer cell lines, we identified TOP2A as a potential indicator of drug response to docetaxel in breast cancer." (PMID 26824188, 2016). "TOP2A is a target gene of two Breast cancer drugs (Epirubicin and Doxorubicin) and of two repurposed drugs from LINCS (Etoposide and Teniposide) which are greater than 80% structurally similar." (PMID 26892392, 2016). "Studies on breast cancer patients indicate that amplification and possibly deletion of TOP2A is predictive of response to epirubicin." (PMID 26867764, 2016). "The clinical relevance of the allelic (im)balance status at the HER2/TOP2A locus in breast cancer is subject of future study." (PMID 26022247, 2015). "Six genes have been reported to contribute to about 44% of driver mutations in breast cancer (copy number increase or amplicons): MYC, FGFR1 (Chromosome 8); CCND1 (Chromosome 11); HER2, TOP2A (Chromosome 17); and ZNF217 (Chromosome 20)." (PMID 26008969, 2015). "Copy number alterations across the genomic region incorporating the HER2/TOP2A locus have been proposed to be a marker for the degree of chromosomal instability in breast cancer." (PMID 26022247, 2015). "The Small cell fraction also showed copy number increases in six target genes (FGFR1, Myc, CCND1, HER2, TOP2A and ZNF217) associated with breast cancer." (PMID 26008969, 2015). "TOP2A gene encodes a 170 KDa nuclear enzyme controlling DNA topological structure and is frequently coamplified with HER2 gene in breast cancer and bladder cancer." (PMID 25695068, 2015). "We further used pooled samples to carry out DNA FISH for six genes previously reported to contribute to driver mutations in breast cancer: MYC, FGFR1, CCND1, HER2, TOP2A, and ZNF217." (PMID 26008969, 2015). "The amplification of TOP2A in breast cancer predicts increased sensitivity to anthracylines in women." (PMID 24023754, 2013). "In the present study we investigated the prognostic role of CEP17 gain in relation to HER2 and TOP2A gene status and protein expression in 1031 patients with operable breast cancer." (PMID 23537287, 2013). "Information regarding the interaction of HER2/TOP2A gene status in the presence of CEP17 gain with the outcome of breast cancer patients is limited." (PMID 23537287, 2013). "This urged us to investigate the prognostic role of HER2 and TopoIIa protein expression, as well as HER2 and TOP2A gene status along with CEP17 gain in a large cohort of breast cancer patients." (PMID 23537287, 2013).
breast carcinoma (continued). "Even though the adverse prognostic role of HER2 parameters (gene amplification and mRNA and protein overexpression) in patients with operable breast cancer is indisputable, that of TOP2A parameters remains controversial." (PMID 22240029, 2012). "Two different TOP2A parameters, gene amplification and mRNA expression, seem to have a distinct impact on the outcome of breast cancer patients treated in the adjuvant setting." (PMID 22240029, 2012). "In advanced-stage HER2-positive breast cancer patients treated with trastuzumab, TOP2A amplification appears to be a strong predictive factor for improved survival in patients with concurrent or previous exposure to anthracyclines." (PMID 23092535, 2012). "Breast cancer with increased TOP2A expression has been reported to be more sensitive to anthracycline." (PMID 21501481, 2011). "Because HER2 and TOP2A are harbored nearby on chromosome 17q21-q22, a high concordance of the HER2 and TOP2A gene co-amplification was indicated in breast cancer." (PMID 22016618, 2011). "It will, therefore, also be interesting to explore how these biomarkers can be utilized as predictors of breast cancer response to TOP2A and antimicrotubule inhibitors." (PMID 21785684, 2011). "Both subtypes I and IV breast cancer in our study indeed had the highest TOP2A expression among the six molecular subtypes." (PMID 21501481, 2011). "In 31% of HER2+ tumors the amplicon extended to TOP2A, defining a subgroup of HER2+ breast cancer associated with estrogen receptor-positive status and with a trend of better survival than HER2+ breast cancers with deleted (18%) or neutral TOP2A (51%)." (PMID 20459607, 2010). "Previous studies showed that TOP2A and HER2 were co-amplified in approximately 30–90% of breast carcinomas; the underlying molecular mechanism for co-amplification is not known." (PMID 19061514, 2008). "Co-amplification of top2A and erb-B2 is often reported in breast cancers, yet in gastric adenocarcinoma, overexpression of top2A was independent and more frequent than of erb-B2." (PMID 19412438, 2007). "In the clinical setting, only a few studies have been published regarding the predictive value of TOP2A amplification in breast cancer patients." (PMID 17088909, 2006). "A positive correlation between FOXM1 and TOP2A expression was found in patients with breast cancer undergoing EC-T chemotherapy, both negatively correlated with STUB1, whose higher expression levels were linked to increased pathologic complete response (pCR) rates." (PMID 41851614, 2026). "Moreover, immunohistochemical staining was conducted to assess STUB1 and TOP2A expression levels, as well as their predictive roles in the efficacy of neoadjuvant chemotherapy in individuals diagnosed with breast cancer." (PMID 41851614, 2026). "Similarly, the protein expression of UBE2C was also positively correlated with that of TOP2A in breast cancer." (PMID 40729680, 2025). "Moreover, TOP2A expression correlated with poor prognosis in patients with breast cancer patients in relation to OS and RFS." (PMID 40729680, 2025). "In breast cancer, TOP2A expression correlates significantly with ER, Ki-67, and HER2 expression." (PMID 39888956, 2025). "Similarly, elevated levels of TOP2A have been observed in colon, liver, pancreatic, ovarian, and breast cancer." (PMID 40732340, 2025). "The retrospective nature of this study and the underrepresentation of specific molecular subtypes further highlight the need for prospective, multicenter validation studies to confirm these observations and refine the prognostic and predictive value of fascin and TOP2A alterations in breast cancer." (PMID 40243780, 2025).